PLK1 (polo like kinase 1)
Diseases named in the same sentence as PLK1 in open-access papers (continued):
Sharing a sentence is not in itself a finding about the gene and the disease.
pancreatic cancer (continued). "Inhibiting Plk1 with BI2356 or volasertib significantly increased ROS levels in KRAS-mutant colon cancer, pancreatic cancer, and cervical cancer cells, while pre-treatment with a ROS scavenger partially reversed volasertib-induced apoptosis." (PMID 40166466, 2025). "METTL3 upregulates PLK1 expression by methylating the PLK1 3'UTR and contributes to the radioresistance of pancreatic cancers in a cell cycle-dependent manner." (PMID 39972266, 2025). "Data from GEPIA2 showed that PLK1 expression was positively correlated with MYC in lung and pancreatic cancer." (PMID 38104151, 2023). "We investigated the effect of PLK1 inhibition on pancreatic cancer cells using NMS-P937, a selective PLK1 inhibitor (PLK1i), which has 5000-fold higher selectivity than PLK2/PLK352." (PMID 35773310, 2022). "The PLK1 inhibitor, rigosertib, entered the clinical research stage at phase II/III for the treatment of pancreatic cancer and glioma." (PMID 36184616, 2022). "Polo-like kinase 1 (PLK1) represents a family member of serine and threonine kinases highly expressed in pancreatic cancer; moreover, increased PLK1 expression correlates with GEM resistance." (PMID 36297407, 2022). "Both PLK1 and ATM regulate the cell cycle, and it is important to determine whether ALDOA, which connects ATM to PLK1, regulates the cell cycle arrest caused by DNA damage and whether this regulatory mechanism is significant in the development of pancreatic cancer." (PMID 34565365, 2021). "In the present study, we demonstrate that KRAS‐mutant lung and pancreatic cancers are highly sensitive to concomitant inhibition of FGFR1 and PLK1." (PMID 34369083, 2021). "Here, we reported, for the first time, that combined treatment with FGFR1 and PLK1 inhibitors evokes synergistic cytotoxic activity in KRAS‐mutant lung and pancreatic cancer models in vitro and in vivo." (PMID 34369083, 2021). "BI-2536 is a polo-like kinase 1 (PLK-1) inhibitor used for the treatments of leukemia, carcinoma, pancreatic neoplasms, and non-small-cell lung cancer." (PMID 35056094, 2021). "Nevertheless, the genetic evidence is in line with our pharmacological results and confirms the synergy of PLK1 and FGFR inhibition in KRAS‐mutant lung and pancreatic cancer cells." (PMID 34369083, 2021). "Further studies revealed that ALDOA expression positively correlates with PLK1 expression and negatively correlates with ATM expression in pancreatic cancer patients." (PMID 34565365, 2021). "Interesting, we found six genes E2F7, CDC6, MMP14, PLK1, VASP and PKM2 were significantly correlated with the prognosis of patients with pancreatic cancer in TCGA, GSE71729, GSE78229 and GSE79668 datasets." (PMID 32950968, 2020). "As described, PLK1 augmented c-fos-mediated induction of MDR1, suggesting that PLK1 reduces GEM sensitivity of pancreatic cancer cells through up-regulation of MDR1." (PMID 29558908, 2018). "To further demonstrate the utility of the PLK1 NanoBRET assay, we profiled adavosertib (MK-1775/AZD1775), a WEE1 kinase inhibitor in clinical development for the treatment of pancreatic cancer, whose kinase selectivity has been the subject of debate in the literature." (PMID 37049713, 2023). "Based on the regulation of PLK1 and IKKβ reported in these two studies, VRK2 might be an important hub of signal transduction in pancreatic cancer." (PMID 35173553, 2022). "Plk1 expression correlated with HIF-1α target in 15 out of 26 available data on cancer types (enough data for robust statistical analysis in 26 out of 32 available cancer types) like melanoma, two types of kidney, head and neck, lung, and pancreatic cancers." (PMID 33547392, 2021). "In addition, the dual expression of high levels of PLK1 and PTEN has aggravated the clinical outcomes of pancreatic cancer patients in GSE78229 and GSE62452." (PMID 31979216, 2020).
pancreatic cancer (continued). "Therefore, we determined the ability of those two anticancer candidates, miR-34a and PLK1-siRNA complexed with our APA nanocarrier, to inhibit the tumorigenicity of pancreatic cancer cells." (PMID 29295989, 2018). "As the most thoroughly studied member of PLK family, PLK1 was reported to accelerate EMT in gastric and pancreatic cancer cells through the PI3K/Akt pathway, whereas the relationship between PLK4 and PI3K/Akt pathway remains unknown." (PMID 29352113, 2018). "Consistently, homozygous XAB2 and PLK1 knockout mice display an early embryonic lethal phenotype and knockdown of XAB2 was reported to induce widespread cell death in human bladder, cervix and pancreatic cancer." (PMID 26755646, 2016). "Interestingly, KRAS‐mutant colon cancer cells appear to show a greater dependency on PLK1 for survival than KRAS‐mutant lung and pancreatic tumor cells, as single treatment with PLK1 inhibitors (e.g., BI2536) is sufficient to induce high levels of ROS and activation of the p38/JNK/E2F1 axis." (PMID 34369083, 2021). "Hence, if overexpression of PLK1 for patients with pancreatic cancer after pancreatectomy was detected, non-gemcitabine chemotherapy would be preferred to avoid potential chemotherapeutic resistance." (PMID 34485300, 2021). "Additionally, PLK1 mRNA levels in high PTEN-expressing group have been significantly up-regulated compared with those in low PTEN-expressing group in GSE78229 and GSE62452 data sets, which had an adverse prognosis of pancreatic cancer patients to elevated PTEN expression." (PMID 31979216, 2020).
melanoma (63 papers, 2004 to 2026). A malignant, usually aggressive tumor composed of atypical, neoplastic melanocytes. "Since BRAF is the most abundant driver mutation in melanoma, we also analyzed the PLK1 expression in patients with melanoma harboring BRAF mutations." (PMID 41284701, 2025). "In a melanoma mouse model induced by BRafCA mutation and Pten-deficiency, we observed that PLK1 overexpression mediated metabolic reprogramming to markedly accelerate tumor growth, promote metastasis, and shortened mice survival." (PMID 41284701, 2025). "To further explore the underlying role of Plk1 in melanoma development, we performed RNA sequencing (RNA-seq) on mouse melanoma tumors." (PMID 41284701, 2025). "To identify the key molecule associated with PLK1 in melanoma, we initially examined transcription factors that are closely linked to OXPHOS." (PMID 41284701, 2025). "To validate the function of PLK1 and understand its underlying mechanisms, we isolated and established 3 pairs of mouse melanoma stable cell lines from our GEM tumors." (PMID 41284701, 2025). "Specific mitochondrial proteins are associated with resistance to treatments targeting polo-like kinase 1 activity or expression in melanoma." (PMID 39658088, 2025). "In this study, we determined the functional significance of PLK1 in EMT in melanoma cells by implementing PLK1 gain-of-function and loss-of-function approaches." (PMID 38184733, 2024). "PLK-1 has also proven promising in other cancers, such as ovarian cancer, where a correlation between PLK-1 expression and clinical stage and grade has been established, and in melanoma, where an association with distant metastases has been demonstrated." (PMID 39857637, 2024). "While treatment with the PLK1 inhibitor volasertib has been shown to cause cell-cycle arrest, decreased cell viability and increased apoptosis in melanoma cells, we have found that this is also true for melanoma cells that are resistant to vemurafenib." (PMID 36768289, 2023). "Using the TCGA dataset, we demonstrated that a high PLK1 expression was associated with significantly worse overall survival in melanoma patients carrying a BRAFV600E mutation." (PMID 36768289, 2023). "In contrast, a recent study in human melanoma cells demonstrated that a targeted knockdown of NUMB expression disrupts its ability to interact with the serine/threonine polo-like kinase Plk1 thereby causing G2–M arrest and reducing cell growth." (PMID 24980814, 2014). "PLK1 expression has also been shown to be a reliable marker for identifying a high risk of metastasis in malignant melanomas." (PMID 22309939, 2012). "To characterize the mitochondrial protein expression patterns associated with resistance to PLK1 inhibition in melanoma cell lines, we performed correlation analyses between transcript expression levels (CCLE) and the impact of PLK1-targeting approaches on cell proliferation (DepMap)." (PMID 39658088, 2025). "To explore the PLK1-associated mechanisms and to identify genes affected by PLK1 signaling in melanoma, we used an Affymetrix microarray to compare the shRNA-mediated PLK1 knockdown in A375 melanoma cell line (A375 shPLK1) with its nonsense control cell line (A375 shNS)." (PMID 38184733, 2024). "The inhibition or loss of PLK1 induces apoptosis in various cancer cells, including melanoma." (PMID 36768289, 2023). "In addition, overexpression of PLK1 in many cancers, including melanoma, ovarian cancer, and others, has been associated with poor prognosis." (PMID 20664703, 2010). "This is also supported by melanoma TCGA data analysis where we found that composite high mRNA expressions of PLK1 and N-cadherin significantly decreased overall survival of melanoma patients, and low PLK1 with high E-cadherin expression was associated with a trend of higher overall survival." (PMID 38184733, 2024).
melanoma (continued). "Because PLK1 has already been shown to contribute to melanoma progression and poorer outcomes in general, we specifically focused on the relevance of PLK1 in BRAF-mutated melanoma and further investigated whether it may serve as a therapeutic target to overcome BRAFi resistance." (PMID 36768289, 2023). "MEK plus Plk1 inhibitors resulted in an additive growth reduction of NRAS‐mutant melanoma in vitro and vivo." (PMID 41492362, 2026). "Herein, we reported a novel PLK1/BACH1 axis as a resistant mechanism in the treatment of melanoma with Vemurafenib." (PMID 41284701, 2025). "In mouse and human melanoma cells with PLK1 overexpression, BACH1 demonstrated a significantly more stable phenotype and an extended half-life." (PMID 41284701, 2025). "In summary, our findings demonstrate that high PLK1 expression promotes metabolic reprogramming, reduces intracellular ROS levels, and enhances the antioxidant ability of melanoma cells." (PMID 41284701, 2025). "Here, we report the identification of mitochondrial protein signatures that determine the sensitivity to approaches targeting PLK1 in human melanoma cell lines." (PMID 39658088, 2025). "We validated the efficacy of PLK1 inhibitor Volasertib in combination with Vemurafenib both in vitro and in vivo, demonstrating strong synergy in suppressing human and mouse melanoma." (PMID 41284701, 2025). "Our analysis has uncovered that high Plk1 is associated with a shortened survival period in patients with melanoma, suggesting a tumor-promoting role of PLK1 in melanoma progression." (PMID 41284701, 2025). "The first evidence of PLK1 as a putative target for melanoma treatment emerged from seminal studies showing increased PLK1 expression in melanoma compared with normal tissue and melanocytes." (PMID 39658088, 2025). "Overall, these findings suggested that high expression of Plk1 contributes to the melanoma growth, metabolic adaptation, and metabolism." (PMID 41284701, 2025). "These cell lines were named mMC (for mouse melanoma cells) and mMPI (for mouse melanoma with Plk1 knock-in), respectively, derived from BrafCA/+/ Ptenloxp/loxp to BrafCA/+/ Ptenloxp/loxp/ Plk1." (PMID 41284701, 2025). "Meanwhile, the silencing of PLK1 in mouse melanoma cells attenuated the expression of the metastatic marker N-Cadherin." (PMID 41284701, 2025). "In mouse models, intratumoral injection of the Cas9/sgPLK-1 plasmid into melanoma-bearing mice significantly downregulated polo-like kinase 1 (PLK-1) protein expression, resulting in over 67% inhibition of tumor growth." (PMID 39942646, 2025). "Once PLK1 was overexpressed, human melanoma cells exhibited an attenuated response to Vemurafenib treatment, along with the increased expression of metastatic markers N-Cadherin and Vimentin." (PMID 41284701, 2025). "While our study reveals a marked heterogeneity in the pro-inflammatory response to RSK/PLK1 inhibitors in nine human melanoma cell lines, most of our experiments compare only two cell lines, MeWo and A-375." (PMID 39658088, 2025). "Overall, the present study highlights the critical role of PLK1 in melanoma progression and demonstrates the potential of PLK1 inhibitors, such as Volasertib, as a promising treatment option for patients with melanoma." (PMID 41284701, 2025). "Herein, we investigated the role of PLK1 in melanoma progression using the genetically engineered mouse (GEM) model BrafCA/+/ Ptenloxp/loxp/ Tyr::CreERT2." (PMID 41284701, 2025). "This increase was comparable to the observed elevation of PLK1 in the melanoma patients with low and high PLK1 expression." (PMID 41284701, 2025). "To investigate the role of PLK1 in melanoma, we first examined its clinical relevance using The Cancer Genome Atlas (TCGA) database." (PMID 41284701, 2025). "In line with our previous finding, PLK1 overexpression impacts the metabolic status of melanoma, leading to the suppression of mitochondrial biogenesis and OXPHOS in cells." (PMID 41284701, 2025).
melanoma (continued). "In parallel, we observed the increased glycolytic capacity and reduced ATP production from respiration when overexpressed PLK1 in human melanoma cell A375 and its derived Vemurafenib-resistant A375R cells." (PMID 41284701, 2025). "This study uses a mouse model of melanoma to show that PLK1 stabilizes BACH1, which transcriptionally regulates genes involved in cancer metabolism and metastasis, independently of the cell cycle." (PMID 41284701, 2025). "Next, we evaluated the role of PLK1 in the BrafCA/+/ Ptenloxp/loxp mouse melanoma model and modulated the Plk1 expression by crossing it with either Plk1-KI or Plk1loxp/loxp mice." (PMID 41284701, 2025). "To investigate the impact of Plk1 on mouse melanoma development, we monitored the tumor growth for both long-term overall survival and at fixed time points." (PMID 41284701, 2025). "In this study, we found that PLK1 regulates melanoma’s metabolic reprogramming, metastasis, and drug resistance by stabilizing BTB domain and CNC homolog 1 (BACH1)." (PMID 41284701, 2025). "Knockout and gene silencing of RSK family members had an overall minimal or insignificant effect on the proliferation of melanoma cell lines, whereas the targeting of PLK1 had a dramatic effect, followed by the targeting of Aurora B, FAK, and CDK2." (PMID 39658088, 2025). "In comparison to BrafCA/+/ Ptenloxp/loxp mice, overexpression of Plk1 resulted in accelerated melanoma progression with a high proliferative rate, higher frequency of metastasis, and worse survival." (PMID 41284701, 2025). "Our study not only highlights PLK1 as a biomarker for poor prognosis in malignant melanoma but also establishes it as a valuable therapeutic target for enhancing the efficacy of Vemurafenib in clinical settings." (PMID 41284701, 2025). "Here, we found that mitochondria shape the response of melanoma cells to PLK1 inhibition by acting as a switch between immunologically silent cell death and pro-inflammatory survival." (PMID 39658088, 2025). "We have identified subsets of nuclear genes that encode mitochondrial proteins that can either enhance or decrease the impact of PLK1-directed treatments (pharmacological inhibition, gene silencing, gene knockout) on melanoma cell proliferation." (PMID 39658088, 2025). "To conclude, these data indicate that PLK1 boosts the metastatic potential and diminishes the effectiveness of treatment in both human and mouse melanomas." (PMID 41284701, 2025). "With overexpressed PLK1, the expression of these targets was significantly boosted in melanoma cells, the effect of which was abolished by the addition of PLK1 inhibitor." (PMID 41284701, 2025). "Of note, RNA-seq results of our study have revealed that overexpression of Plk1 promotes metastasis and metabolic reprogramming in melanoma GEM tumors." (PMID 41284701, 2025). "Polo-like kinase 1 (PLK1), a serine/threonine kinase, is overexpressed in melanoma and its expression has been associated with poor disease prognosis." (PMID 38184733, 2024). "Inhibition of endogenous PLK1 by shRNA-mediated knockdown decreased cell proliferation, migration, and invasion of shPLK1 melanoma cells compared to the control cells." (PMID 38184733, 2024). "In this study, Affymetrix microarray analysis was performed to determine differentially expressed genes following shRNA-mediated knockdown of PLK1 in human melanoma cells that showed significant modulations in EMT and metastasis-related genes." (PMID 38184733, 2024). "Using the GEPIA database, we found that the expression of TYMS and PLK1 were significantly upregulated in melanoma." (PMID 39353904, 2024). "This system, designed to target the Plk-1 gene in melanoma cells, utilizes AuNPs for photothermal release of the CRISPR/Cas9 components." (PMID 38607007, 2024).